CRP (C-reactive protein)
Diseases named in the same sentence as CRP in open-access papers (continued):
Sharing a sentence is not in itself a finding about the gene and the disease.
cancer (continued). "Clinical trials on quercetin have shown multiple effects, such as anti-inflammatory effects through the reduction in plasma C-reactive protein or oxidative stress markers, anti-cancer effects, and cancer chemoprevention." (PMID 32629966, 2020). "This is in line with previous studies investigating the prognostic impact of pretreatment CRP levels in cancer patients treated with ICI." (PMID 32824580, 2020). "Inflammation- and nutrition-based prognostic scores, such as the NLR, GPS, mGPS, and CRP/Alb ratio have been reported to have prognostic values in many types of cancer." (PMID 33317455, 2020). "CRP is often raised in cancer and haemoglobin often lowered, further complicating interpretation of these tests." (PMID 32418993, 2020). "Another study performed on a similar population concluded that exercise training had positive effects on C-reactive protein, a widely known cancer marker." (PMID 33371214, 2020). "Our goal was to review the available evidence - generated by us and by others – that supports targeting of CRP as a therapeutic approach for the treatment of human diseases including cancer." (PMID 33633738, 2020). "C-reactive protein, tumor necrosis factor, and interleukin-1 are involved in the pathogenesis of cancer, and can decrease serum albumin concentrations." (PMID 33215031, 2020). "A consensus understanding of what divergent CRP levels indicate in individual cancer cases as related to both the disease and the progression of disease has been lacking." (PMID 33013897, 2020). "Subsequent studies further refined the mGPS to the HS-mGPS using a further lower threshold for CRP (cut-off value: 0.3 mg/dl), in order to enhance the predictive ability of inflammation-based prognostic systems in cancer patients." (PMID 33227100, 2020). "Cachexia is characterized by the activation of systemic inflammation, which is reflected by increased serum levels of C-reactive protein; however, the catabolic drive during cancer cachexia can also be reflected by other cytokines, including IL-6 and TNFα." (PMID 32708527, 2020). "C-reactive protein (CRP) and fibrinogen are acute-phase proteins that are used to represent low-grade inflammation and associated with cancer incidence and mortality." (PMID 33243216, 2020). "Combination of these inflammatory markers into a CRP/Alb ratio had been demonstrated as a prognostic indicator in several kinds of cancers, such as colorectal, gastric, esophageal, hepatocellular, and pancreatic." (PMID 32856868, 2020). "In retrospective studies, the C-reactive protein (CRP) has been associated with poorer prognosis in NSCLC and other cancers." (PMID 33287347, 2020). "Population studies have established that high CRP levels associate with increased cancer risk, increased cancer progression, and increased cancer mortality, and in many cases CRP has been shown to be an independent prognostic factor for cancer." (PMID 33633738, 2020). "If we consider the relationship between the examined proteins and tumor stage, the highest concentrations of CXCL-8, CEA, and CRP were found in patients with stage IV cancer." (PMID 32192002, 2020). "In recent years, indices based on CRP and PA levels, such as the Glasgow Prognostic Score or the CRP/PA ratio, have shown high prognostic predictability for several cancer types." (PMID 32209087, 2020). "Characteristics of cancer patients meeting the criteria CRP ≥ 0.5 mg/dL; plasma albumin <3.2 g/dL; hemoglobin <12 g/dL; or none of the criteria." (PMID 32850383, 2020). "According to our data, there is a high mortality rate in canine patients (80%) as it is known for human cancer patients with CRP > 100 mg/l." (PMID 32434519, 2020). "We observed abnormal CBC, increased liver enzymes, and high CRP occur more commonly in cancer patients than in the control group." (PMID 33334375, 2020). "Virchow has reported that inflammatory reactions and cancer, several studies have found that CRP level is a prognostic factor in a variety of cancer." (PMID 32676164, 2020).
cancer (continued). "Albumin and common laboratory tests for inflammation (e.g. CRP and white cell counts) are useful as predictors of prognosis in people with cancer e.g. Glasgow Prognostic Score." (PMID 32366995, 2020). "Dysregulation of circulating inflammatory markers and cytokines such as interleukin-1 receptor antagonist (IL-1RA), interleukin-6 (IL-6) and C-reactive protein (CRP) has been reported in cancer patients and survivors experiencing CRF." (PMID 33187543, 2020). "These last two groups differed significantly from the cancer-free survivors with regard to their serum CRP levels (p = 0.003), frequency of large tumors at the time of diagnosis (p < 0.001), and frequency of Fuhrman G3-G4 nuclear grading (p = 0.001)." (PMID 32707675, 2020). "The CRP level increases in subsequent subgroups of cancer grade, but was significantly higher only for patients with G3 (p = 0.0268) in comparison to the control." (PMID 30828780, 2020). "Associations between blood transfusion, postoperative C-reactive protein (CRP), albumin, hemoglobin, complications, cancer-specific survival and overall survival (OS) were assessed using propensity score matching (n =116)." (PMID 31664621, 2020). "While CRP’s role in the pathogenesis of cancer remains elusive, it has been suggested to contribute to the growth of breast density by stimulating local estrogen production." (PMID 33004039, 2020). "Many inflammatory markers, such as CRP, NLR, and PLR have been associated with poor prognosis for various cancers." (PMID 32984018, 2020). "The Glasgow prognostic score (GPS) is an inflammation-based prognostic system involving only serum C-reactive protein (CRP) and albumin, and widely considered to be one of the most useful scoring systems for prognostication of patients with various cancers." (PMID 30046949, 2019). "Smoking, pulmonary infection, histological types of cancer, lesion location, neutrophil percentage, CRP, APTT, HDL-C, alanine aminotransferase, and apolipoprotein-E were statistically different as assessed by univariate analysis." (PMID 30931321, 2019). "One study assessed 121 biomarkers related with inflammation, cancer, and cardiovascular disease and five studies assessed CRP." (PMID 31205673, 2019). "If the repeat test was normal the cancer incidence fell to 1.98% (1.49–2.47) for CRP, 2.49% (1.73–3.26) for ESR, and 1.32% (0.34–2.29) for PV." (PMID 31015558, 2019). "In patients with cancer cachexia, elevations of acute phase reactants, such as C-reactive protein (CRP), fibrinogen and inversely albumin, have been correlated with disease progression, decreased survival and poor quality of life." (PMID 31842339, 2019). "In-depth studies of the tumor–inflammation link have identified several blood markers as potential indicators of systemic inflammation and predictors of prognosis in patients with cancer, including the dNLR, C-reactive protein, albumin and LDH." (PMID 31024844, 2019). "Research has discovered that CRP produces inflammatory cytokines and chemokines, which lead to cancer progression." (PMID 31644587, 2019). "Out of 506 people with ESR ≥ 100, 69 (13.6%) developed cancer in 1 year; with CRP ≥ 100 (n = 1983), 135 (6.81%) developed cancer; with PV ≥ 2.0 mm/h (n = 342), 31 (9.06%) developed cancer." (PMID 31015558, 2019). "Previous studies have suggested that some inflammatory factors such as CRP, interleukin-6 and neutrophil to lymphocyte ratio can predict the prognosis in cancer patients." (PMID 31815279, 2019). "Serum CRP and albumin are indicators of chronic inflammation and poor nutritional status of cancer patients." (PMID 31644587, 2019). "The CRP level in the cancer group was significantly higher than the levels in the benign tumour, non‐tumour disease and healthy groups (all P < 0.0001, Kruskal‐Wallis test)." (PMID 30411459, 2019).
cancer (continued). "Biomarkers of the systemic inflammatory response (albumin and CRP combined in the modified Glasgow prognostic score (mGPS)) predict survival in cancers with an established site." (PMID 31591445, 2019). "A cross-sectional investigation observed that deprived glutamine levels are not only associated with a poor nutritional status (p = 0.0438), but also fatigue severity (p = 0.0303) and inflammation (CRP; p < 0.0001) in patients undergoing cancer treatment." (PMID 31574939, 2019). "GPS is based on the combination of CRP and albumin levels and helps it as a significant prognostic factor in patients with cancer, reflecting both inflammatory components and nutritional status." (PMID 31038863, 2019). "Serum CRP levels have been shown to be elevated in patients with multiple types of cancers, and, in particular, elevated serum CRP levels have been associated with poor survival." (PMID 31260491, 2019). "The median CRP levels in the cancer, benign tumour, non‐tumour disease, and healthy groups were 12.64 (range: 0.5‐348) mg/L, 4.61 (range: 1.1‐178.8) mg/L, 3.47 (range: 0‐170.4) mg/L and 2.3 (range: 0.27‐18.03) mg/L, respectively." (PMID 30411459, 2019). "In the present study, the NI had a higher AUROC and higher sensitivity, specificity, and accuracy than ECPKA‐Ab alone, indicating that ECPKA‐Ab is a more powerful biomarker of cancer when combined with CRP." (PMID 30411459, 2019). "C-reactive protein (CRP) has been extensively studied as a marker of inflammation and more specifically as a risk indicator for cardiovascular, cancer, and all-cause mortality." (PMID 30569368, 2019). "The aim of this study was to evaluate ECPKA‐Ab and C‐reactive protein (CRP) as serum biomarkers for cancer in dogs." (PMID 30411459, 2019). "Serum C-reactive protein (CRP) level has been shown to be a predictor of survival for multiple cancer types." (PMID 31260491, 2019). "If the second test was lower than the first, but still above the normal range, the cancer incidence was 4.35% (3.66–5.04) for CRP, 3.55% (2.86–4.24) for ESR and 3.28% (1.79–4.78) for PV." (PMID 31015558, 2019). "ECPKA‐Ab and CRP levels were significantly higher in the dogs with malignant tumours than in those with benign tumours or non‐tumour diseases, as well as in the healthy controls (P < 0.001, Kruskal‐Wallis test)." (PMID 30411459, 2019). "The Glasgow inflammation score consisting of CRP and albumin, and has been shown to be an independent prognosticator for several cancer types, including HCC." (PMID 30662766, 2019). "C-reactive protein (CRP), a major acute-phase protein, is generally considered as an indicator for low-grade systemic inflammation in chronic diseases such as cancer and cardiovascular disease (CVD)." (PMID 31485456, 2019). "In 1161 RCC patients who underwent surgery, multivariate analysis revealed that CRP level is an independent prognosticator for cancer-specific survival (HR = 1.007, 95% CI = 1.004–1.009, p < 0.001) as well as OS (HR = 1.006, 95% CI = 1.004–1.008, p < 0.001)." (PMID 31443339, 2019). "Levels of CRP and albumin have been considered as possible prognostic factors of cachexia development for patient with cancers." (PMID 30941358, 2019). "Emerging evidence also suggests that CRP can predict cancer prognosis and survival in cohort studies, and CRP has better predictions than other traditional inflammatory indexes." (PMID 31443226, 2019). "In particular, CRP is extensively reported in oncology as a reliable biomarker for survival, cancer risks, and tumor recurrence, impacting on many critical decisions in treatment." (PMID 30923859, 2019). "Thirteen of 130 patients were excluded due to active cancer disease, 7 patients because of a missing CRP value at the time of catheter implantation." (PMID 31151433, 2019). "As the most sensitive inflammatory biomarker, C-reactive protein (CRP) has been confirmed in a series of cancers to predict the prognosis, including EC." (PMID 31379941, 2019).
cancer (continued). "CRP has been shown to induce the expression of acute-phase proteins such as neutrophils and predict poor prognosis in several cancers." (PMID 31443339, 2019). "Similar to our study, several reports have shown a decrease in the mDC or/and pDC count in inflammatory diseases, such as septic shock, influenza A, and C-reactive protein-producing carcinoma." (PMID 30879162, 2019). "Several of the studies investigated in this review assessed the correlation between serum IL-6 and CRP levels in cancer patients, and the majority found a significant correlation between IL-6 and CRP." (PMID 30038723, 2018). "The inflammatory factors are mainly derived from the secretion of both host and tumor cells, and the systemic reaction to cancer cells, including some chemokines and cytokines, transcription factors, CRP, circulating immunocytes, and so on." (PMID 30258731, 2018). "The causes of the latent inflammatory responses in the patients with serum CRP > 0.5 mg/dL were thought to be chronic infections, malignant tumors, latent aspiration, or autoimmune responses." (PMID 30305016, 2018). "This study aims to add to the ongoing discussion regarding the definition of cancer cachexia and to study the role of C-reactive protein and s-albumin in this context." (PMID 29534089, 2018). "The implication of our findings is a stricter cut off for CRP when defining cancer cachexia than what has previously been suggested." (PMID 29534089, 2018). "The search for patterns (periodic or otherwise) in the CRP time-series is of interest for providing a cue for the optimal times at which cancer therapies are best administered." (PMID 30097610, 2018). "Particularly, CRP, IL-6 and TNF-α, in particular, have been reported to be associated with a variety of cancers." (PMID 29844870, 2018). "Note that CRP is widely reported in oncology as a marker for survival, an indicator of cancer risk, as a biomarker for tumour recurrence, and as a reliable tool for making critical decisions in treatment." (PMID 30097610, 2018). "One study investigating inflammation levels after cancer treatment found that C-reactive protein and cytokine levels were elevated up to 5 years after treatment." (PMID 30442190, 2018). "It appears that even one elevated CRP in a cancer patient (unexplained by a co-morbid illness or other intercurrent event) suggests a significantly worse disease outcome." (PMID 30138391, 2018). "Approximate 90% of normal populations have a serum CRP concentration of less than 0.3 mg/dl, while cancer patients represent a significantly higher serum CRP level." (PMID 29568406, 2018). "This suggests the need for a revised CRP reference range of 1–5 mg/L for prognostication in cancer patients." (PMID 30138391, 2018). "Meta-analyses have demonstrated that IL-6, TNF, and CRP are elevated in non-cancer patients with depression disorder." (PMID 30266081, 2018). "The albumin and HDL levels were significantly lower and the triglyceride, VLDL and CRP levels were significantly higher in cancer patients compared with control patients (p < 0.05)." (PMID 29941786, 2018). "IMMUNEPOTENT CRP (I-CRP) is a dialyzable bovine leukocyte extract that contains transfer factors and acts as an immunomodulator, and can be cytotoxic to cancer cell lines and reduce tumor burden in vivo." (PMID 29298674, 2018). "Laboratory measures that imply the presence of cancer cachexia (CRP and s-alb) had a median onset of 47 days prior to death and during the last month in life were altered in 85% of the patients." (PMID 29534089, 2018). "Some studies have demonstrated a potential role of inflammation (CRP, IL-6) for general cancer pain." (PMID 30266081, 2018). "Deficiencies in certain vitamins correlate with systemic inflammation assessed by C-reactive protein (CRP) in cancer patients." (PMID 30189611, 2018). "Not surprisingly, multiple acute phase reactants have been demonstrated to be correlated with poor prognosis in cancer (e.g. CRP, SAA)." (PMID 29558888, 2018).
cancer (continued). "Given that the CRP/albumin ratio also shows various cut-off values depending on cancer type and severity, further studies will be needed to better understand the optimal cut-off value for the hsCRP/albumin ratio in different clinical scenarios." (PMID 29880755, 2018). "This review will discuss studies that utilized neutrophil-to-lymphocyte ratio (NLR), platelet-to-lymphocyte ratio (PLR), and CRP to determine their value for cancer detection and prognosis." (PMID 29619344, 2018). "We also investigated the impact of GPS, an inflammation-based cancer prognostic factor calculated from the values of CRP and albumin, on MPV and LMR." (PMID 30192878, 2018). "CRP identifies homeostatic immune oscillations in cancer patients: a potential treatment targeting tool?" (PMID 30400835, 2018). "The GPS is a selective combination of CRP and albumin serum levels that has been examined and validated in more than 60 studies for a variety of cancers." (PMID 29581844, 2018). "Even though cancer patients were excluded, the AUC of CRP/albumin ratio was higher than that of CRP for mortality in critically ill patients (0.585 vs. 0.559, p < 0.001)." (PMID 30297655, 2018). "We discussed the relationship between inflammation and cancer and described the notable blood measurements, such as platelets, neutrophils, lymphocytes, their relative ratios, and CRP." (PMID 29619344, 2018). "Only the statistically significant variables of CRP, BMI and cancer family history were analysed further to explore their associations with the glycan traits." (PMID 29872119, 2018). "The present study revealed elevated serum CRP levels in patients with malignancy compared to patients with PMDs and the control group." (PMID 30842796, 2018). "Yet, there is not total agreement in the literature over the prognostic utility of CRP in select cancer types." (PMID 29619344, 2018). "Active cancer treatment was found to directly affect various laboratory markers, including acute phase reactant (c-reactive protein (CRP), erythrocyte sedimentation rate (ESR)), albumin, and neutrophil, lymphocyte, monocyte and platelet counts." (PMID 30231854, 2018). "Since CRP is considered a disease marker for various diseases, including malignant tumors, the epigenetic effect of high-CRP conditions over the long term is a reasonable research question." (PMID 29439678, 2018). "There remains a need for larger studies to be conducted to define the importance of CRP as a biomarker for informing cancer staging and prognosis." (PMID 29619344, 2018). "The C-reactive protein/albumin ratio (CRP/Alb ratio) has been reported to have promising prognostic value in several cancers." (PMID 30352836, 2018). "The second one is reverse—it suggests that CRP and inflammation processes contribute to cancer development and progression." (PMID 30065196, 2018). "With the presence of elevated serum CRP concentration, serum level of vascular endothelial growth factor is also increased, which plays a critical role in promoting cancer angiogenesis and improving oxygen supply of cancer cells." (PMID 29568406, 2018). "We decided to investigate the relationship between CRP level and prognosis utilizing the electronic medical records of 4931 persons with solid tumors who had CRP measured subsequent to their cancer diagnosis." (PMID 30138391, 2018). "Results obtained in our laboratory show that a type of bovine DLE obtained from disintegrated spleen, IMMUNEPOTENT CRP© (I-CRP), is cytotoxic to several cancer cell lines." (PMID 29298674, 2018). "An inverse correlation of BChE and the inflammatory markers CRP and IL-6 has been reported in a non-cancer cohort." (PMID 29113384, 2017). "There is Grade A evidence that elevated serum CRP is an independent prognostic factor in advanced cancer." (PMID 28384249, 2017). "This indicated that the serum CRP levels are stable in OSCC cancer patients, and so, the serum level analyzed in our study was not amenable to change in a different time period." (PMID 28209200, 2017).